RNU6-171P (RNA, U6 small nuclear 171, pseudogene)
Gene: Small nuclear RNA gene on chromosome 1 (164,639,565 to 164,639,671, forward strand). Ensembl gene ENSG00000207082.
Homologues: Orthologues: chimpanzee U6 (98% identical), macaque U6 (90% identical). Paralogues in human: RNU6-19P (85% identical), RNU6-301P (84% identical), RNU6-35P (84% identical), RNU6-43P (84% identical), RNU6-144P (83% identical), RNU6-25P (83% identical), RNU6-761P (83% identical), RNU6-820P (83% identical), RNU6-1 (82% identical), RNU6-1010P (82% identical), RNU6-1091P (82% identical), RNU6-1152P (82% identical), and 1284 more.